SIRT1 (sirtuin 1)
Diseases named in the same sentence as SIRT1 in open-access papers (continued):
Sharing a sentence is not in itself a finding about the gene and the disease.
infection (continued). "RSV infection of SIRT1-/- BMDC induced significantly higher Il1β, Il6 and Il23 expression early in the infection as compared to WT+RSV." (PMID 32106265, 2020). "Decreased expression of SIRT1/Sirt1 was also found in M. tuberculosis-infected THP-1 cells and in mouse lungs, and its activation contributed to control of infection by the host cells." (PMID 30914513, 2019). "To further implicate SIRTs in the control of infection, we obtained flies harboring a CRISPR deletion in Drosophila SIRT1 (dSIRT1) (2a-7-11) or dSIRT2 (5B-2-35)." (PMID 31289184, 2019). "We further assessed the expression in a later point of infection (24 h) of three targets of miR-217 during OROV infection: DCP2, MAPK1 and SIRT1." (PMID 29813068, 2018). "Immunofluorescence analysis showed that Sirt1 co-localized with LKB1 in uninfected cells, during the early (1h) and late phase of infection (4h)." (PMID 28192515, 2017). "SIRT1 mRNA and SIRT1 protein were upregulated by EV71 starting at 3 h post-infection (hpi) (P<0.05) and further increased by EV71 infection at an multiplicity of infection (MOI) of 2 in RD cells (P<0.05)." (PMID 27875274, 2016). "We examined the impacts of SIRT1 activator resveratrol (RES) and its inhibitor nicotinamide (NIC) on HMGB1 release and PEDV infection." (PMID 27634894, 2016). "We measured CX3CL1 mRNA levels in cells following infection in the presence of HDAC inhibitors, TSA (for HDAC1/2) and EX527 (for HDAC3 type Sirt1)." (PMID 23724129, 2013). "Conversely, CpG sites related to Slc11a1, Havcr2, Ccl11, Ccl12, Sirt1, Ifng, Ccl3, Ror2, and Trem2 maintained lower methylation levels throughout the infection compared to noninfected samples." (PMID 40170749, 2025). "We did not detect changes in gene transcription levels duringHPV infection, including those of SIRT1." (PMID 40584241, 2025). "In early infection stages, increased ACE2 expression by SIRT1 may enhance SARS‐CoV‐2 viral entry, potentially elevating susceptibility to infection." (PMID 41416347, 2025). "We even monitored the expression profile of Sirt1 and Sirt3 in primary macrophages like peritoneal macrophages of C57BL/6 mice and observed a similar trend of elevated expression at initial (2 hr), middle (6 hr), and late (16 hr) time points post-infection." (PMID 39693143, 2024). "However, at the protein level, only SPI-2 mutant infection resulted in a predominant decline in SIRT3 expression and a mild reduction in SIRT1 expression." (PMID 39693143, 2024). "Salmonella modulates the expression of SIRT1 and SIRT3 along its course of infection." (PMID 39693143, 2024). "Leptomycin-B treatment inhibited transcription factor-EB, the master transcriptional regulator of autophagy translocation upon refeeding, as expected, but it did not obstruct SIRT-1 translocation induced by EV-D68 infection." (PMID 37850626, 2023). "In addition, a small group of transcription factors was predicted to be inhibited only upon infection with amastigotes (SOX6, RUNX3, and STAT1) or promastigotes (TRIM24, SIRT1, and FOXP3)." (PMID 35430587, 2022). "Expression of genes encoding chromatin-modifying enzymes such as: methyltransferases, acetylases and deacetylases, including SIRT1, are altered in HIV-infected individuals, in order to create an appropriate environment for virus replication and the progression of infection." (PMID 34685718, 2021). "Infection with Ad-circ-Sirt1 did not affect IκBα phosphorylation or degradation following TNF-α stimulation compared to the Ad-Vector-infected control group." (PMID 30820544, 2019).
infection (continued). "To confirm that SIRT1/FAK influence the functional activation of Mφ in response to Tc infection, we incubated RAW Mφ for 24 h with or without Tc (±SRT1720 or iFAK) and monitored the cytokines’ gene expression by RT-qPCR." (PMID 31905606, 2019). "However, during the later stages of infection, HSV-1 induces apoptosis of host cells concomitantly with Sirt1 activation." (PMID 30404221, 2018). "We also observed that Sirt1 and LKB1 co-localized on SCV shaped vesicles at 1h post infection." (PMID 28192515, 2017). "Furthermore, infection of Ad-Flag-HMGB1K282930R and Ad-Myc-SIRT1 almost completely abolished LPS-induced secretion of these cytokines, yielding levels similar to those in the control group." (PMID 26522327, 2015). "Here, we demonstrated that in the absence of a catalytically active SIRT1, infected macrophages display a similar transcription and infection phenotype as AMPK KO cells." (PMID 25738568, 2015). "All 3 shRNAs against either SIRT1 or SIRT2 significantly reduced their target RNA levels and protein accumulation in the infected cells 48 hours after the last infection of these viruses." (PMID 23460888, 2013). "Furthermore, it is imperative to consider that HIV-1 Tat-induced inhibition of SIRT1 does not occur at the onset of infection." (PMID 38139395, 2023). "However, we found that the autophagy kinase regulator RB1CC1 does not leave the nucleus during EV-D68 infection, indicating that SIRT-1 is being targeted for translocation." (PMID 37850626, 2023). "Indeed, numerous studies have shown the function of SIRT1/AMPK axis in the autophagy regulation, although it remains largely unknown in the context of infections." (PMID 36139497, 2022). "Treatment with SIRT1 agonist suppressed the FAK phosphorylation, and FAK-dependent increase in Pu.1 and Runx1 involved in Mφ proliferation and polarization, and also suppressed the NFκB activity required for proinflammatory activation of Mφ in response to Tc infection." (PMID 31905606, 2019). "To understand whether the enzymatic domain of SIRT1 possess any role in mediating this interaction, we carried out NF-κB p65 immunoprecipitation in infected RAW 264.7 macrophages in the presence or absence of SIRT1 catalytic chemical inhibitor, EX-527 (1 μM) treatment at 16 hr post-infection." (PMID 39693143, 2024). "Following infection with these adenoviruses, the levels of exogenous HMGB1 and SIRT1 proteins were similar in the presence and absence of LPS." (PMID 26522327, 2015). "Infection of the floxed primary myoblasts with Cre, but not with GPF significantly reduced the activity of SIRT-1." (PMID 25361036, 2014). "Since inhibition of SIRT1 or SIRT2 was not sufficient, we also tested the combination of EX527 and AGK2 to determine whether that combination could block infection." (PMID 31289184, 2019). "As Leishmania-infected BMMo AMPK can be activated with AICAR in the absence of SIRT1, the treatment with AICAR led to a significantly increase on infection levels, while the concomitant addition of compound c abrogated this infection rise to levels of untreated cells." (PMID 25738568, 2015).
kidney diseases (106 papers, 2011 to 2025). "These researches suggest that ferroptosis can be effectively inhibited by regulating SIRT1 and its associated signaling pathways, providing a new therapeutic strategy for the treatment of kidney diseases caused by different causes." (PMID 40109363, 2025). "Glomerular SIRT1 expression is reduced in human diabetic glomeruli; the podocyte-specific loss of SIRT1 increased albuminuria and accelerated kidney disease progression in T1DMc OVE26 mice." (PMID 32102312, 2020). "The podocyte-specific loss of sirtuin-1 reduced podocyte numbers, exacerbated albuminuria, and accelerated renal disease progression in diabetic mice." (PMID 33519447, 2020). "Consistent with this, we have shown recently SIRT1 deficiency in podocytes aggravates aging-related kidney disease through enhanced cells senescence and mitochondrial dysfunction." (PMID 30386303, 2018). "Defective SIRT1 activity has been described in various cardiovascular, renal diseases and in aging-associated conditions." (PMID 30298020, 2018). "Endothelial SIRT1 deficiency is a common companion of various cardiovascular, metabolic and renal diseases, as well as of aging." (PMID 30298020, 2018). "A large body of evidence suggests that SIRT1 plays a major role in various kidney diseases by providing protection against cellular stresses associated with kidney injury." (PMID 30386303, 2018). "It is probable that genistein improves I/R-induced renal-injury in a SIRT1-dependent manner, making it a potential reagent for treatment of kidney disease with deficiency of SIRT1 activity." (PMID 28425936, 2017). "Of note, while Sirt1, Sirt2 and Sirt3 are involved in renal diseases, renal hypertrophy and fibrosis in mice deficient in these genes have not been reported." (PMID 28351995, 2017). "In this regard, the regulatory mechanism by which repressed Sirt1 augmented Claudin-1 is considered significant for establishing the potential of diagnostic markers and/or therapeutic targets of the Sirt1/Claudin-1 axis in kidney diseases." (PMID 38587753, 2024). "However, most of the studies are performed in Sirt1 deficient animals and these studies can only show the association of Sirt1 deficiency with kidney disease." (PMID 35795148, 2022). "Interestingly, the podocyte-specific loss of SIRT1 (SIRT1pod−/−) decreased the podocyte numbers and worsened albuminuria, which in turn accelerated renal disease progression in diabetic mice." (PMID 35277012, 2022). "Accordingly, the activation of SIRT1 in the kidney may be a new therapeutic target to rectify independent risk factors of renal diseases, especially OBH renal damage." (PMID 35668772, 2022). "Hence, our results provided further experimental basis for the potential use of genistein for the treatment of kidney disease with deficiency of SIRT1 activity." (PMID 28425936, 2017). "With regard to kidney function, a growing body of evidence from in vitro and animal studies has confirmed the crucial role of SIRT1 in renal diseases." (PMID 41009597, 2025). "In renal disorders, SIRT1 enhances cell survival in damaged kidneys, helps regulate blood pressure, prevents cellular apoptosis in renal tubules, and triggers autophagy." (PMID 40723868, 2025). "Recent studies have highlighted the key role of SIRT1-mediated ferroptosis in multiple kidney diseases." (PMID 40109363, 2025). "Accumulating evidence has demonstrated that SIRT1 regulates oxidative stress and mitochondrial homeostasis in a variety of kidney diseases, including HN." (PMID 39726785, 2024). "Sirt1 depletion in vascular endothelial cells mediates endothelial dysfunction and premature aging in renal disease." (PMID 38347622, 2024).
kidney diseases (continued). "Continuous research on sirtuin family members has led to the development of modulators targeting sirtuins, such as resveratrol and curcumin, which improve renal disease by activating Sirt1 and Sirt3." (PMID 38347622, 2024). "Studies have shown that SIRT1 plays an important role in the pathogenesis of kidney diseases, and high expression of SIRT1 can reduce the acetylation level of NF-κB." (PMID 38073545, 2023). "Recent studies conducted in human podocytes showed that AGEs enhanced the acetylation of key transcription factors via the downregulation of SIRT1, leading to podocyte apoptosis and consequently kidney diseases." (PMID 36866277, 2023). "In vivo and in vitro evidence shows that Sirt1 can serve as an important potential pharmacological target in kidney disease." (PMID 36052119, 2022). "SIRT1 was recently identified as a novel molecular target for the prevention and treatment of several renal diseases, including DN." (PMID 35721758, 2022). "Meanwhile, SIRT1 has been identified as a novel molecular target for the prevention and treatment of kidney diseases." (PMID 35721758, 2022). "SIRT1 is a highly conserved NAD+‐dependent deacetylase known to have protective effects against a variety of renal diseases." (PMID 35137552, 2022). "Accumulating evidence has demonstrated that SIRT1 regulates blood pressure, glucose-lipid metabolism, and sodium balance, which also played an important role in kidney diseases." (PMID 35668772, 2022). "In a study on the relationship between SIRT1 and kidney disease, the expression levels of SIRT1 in the kidney tissues of diabetic rats were found to be significantly downregulated." (PMID 33897448, 2021). "SIRT1 has been shown to exert protective effects in kidney diseases and in AKI, mainly due to its activity on mitochondrial function and to its activation of pgc-1α." (PMID 34061900, 2021). "Apart from scavenging ROS, resveratrol also has many protective effects against age-related disorders, including kidney disease, through activation of Sirtuin 1 (SIRT1)." (PMID 34307650, 2021). "Sirt1 is a well-known functional gene involved in renal diseases through regulating various cellular biological process, such as apoptosis, autophagy, inflammation and mitochondrial biogenesis." (PMID 34580283, 2021). "Many studies have revealed that SIRT1 can mitigate renal disorders via multiple mechanisms, such as reducing oxidative damage, preventing the development of fibrosis, or maintaining mitochondria function." (PMID 34097717, 2021). "Studies in kidney diseases have found that Sirt1 is abundant in renal tissues and contributes to reduce acute kidney injury, alleviate renal fibrosis and delay renal aging." (PMID 34580283, 2021). "In light of these data, we have also observed marked decreases in both patients with albuminuria and stressed podocyte cultures that reinforces the SIRT1 role in kidney disease progression." (PMID 32887498, 2020). "Sirt1 downregulation is likely to contribute to programming of renal disease after early transient postnatal overfeeding." (PMID 32523548, 2020). "SIRT1 is an important regulator that provides renoprotective effects against various renal disorders, but its role in hypertensive renal injury has rarely been studied." (PMID 32419819, 2020). "Of the seven sirtuins, sirtuin-1 has been one of the most extensively investigated in kidney diseases, and its renoprotective effects have been consistently demonstrated in experimental DN." (PMID 33519447, 2020). "Another report by Inagi and colleagues has demonstrated that podocyte-specific Sirt1 knockout provoked podocyte damage in mice, further supporting the ciritical role of SIRT1 in protection against kidney disease." (PMID 30859351, 2019). "Recently, the function of SIRT1 in the occurrence and development of renal disease has been of increasing concern in humans." (PMID 30110438, 2018).
kidney diseases (continued). "Recently, increasing numbers of studies have focused on the involvement of Sirt1 in kidney diseases and Sirt1 has become a promising target for DN treatment." (PMID 29867511, 2018). "We and others have showed the beneficial advantages of Sirt1 on the treatments for various kidney diseases through regulating metabolic disorder, inflammatory and anti-oxidative responses." (PMID 29867511, 2018). "A protective role of SIRT1 has been reported in both podocytes and renal tubular cells in multiple kidney disease settings, including diabetic kidney disease (DKD)." (PMID 30386303, 2018). "Recently, increasing studies have suggested that SIRT1 is a novel target to prevent kidney diseases." (PMID 28852469, 2017). "Many studies have shown that Sirt1 promotes autophagy-mediated processes which have positive effects for antiviral immune responses, cytotoxicity, hepatosteatosis and kidney disease." (PMID 26918354, 2016). "Resveratrol, another class of polyphenol, has been shown to play the protective role in kidney disease through up-regulating Sirt1 level." (PMID 27455216, 2016). "Given its important role in the tissue repair and regeneration, the observed downregulation of SIRT1 in the renal tissue of the untreated anti-GBM-GN mice is likely contributed to progression of kidney disease in this model." (PMID 25785827, 2015). "Since the first description of the Sir2 family and its effects on longevity in yeast, our understanding of the specific actions and role of SIRT1 on different kidney diseases have increased tremendously." (PMID 25346724, 2014). "Transcription factors that are targeted by Sirt1 and also play a significant role in the pathophysiology of kidney disease include Smad7, HIF-2α, and Stat3." (PMID 21858169, 2011). "In fact, Sirt1 plays a positive role in various kidney diseases." (PMID 40824734, 2025). "Sirtuin-1 (SIRT1) deacetylase, which is abundantly found in renal tissues, has a role in kidney disorders by controlling a number of cellular biological processes, including apoptosis, autophagy, and inflammation, which helps to lessen acute kidney damage and treat kidney fibrosis." (PMID 37841018, 2023). "Sirtuin-1 regulates mammalian oxidative respiration, anti-inflammatory responses, and redox signaling pathways; the latter is critical in regulating the pathogenesis of various diseases, including kidney diseases." (PMID 36615896, 2023). "Since sirtinol, a Sirt1 inhibitor, nullified the effects of H2, Sirt1 may be involved in the protective effects of H2 on renal disease." (PMID 37893190, 2023). "Moreover, a study also has shown that curcumin alleviates aristolochic acid-induced nephropathy and tubular cell apoptosis via Sirtuin-1-Nrf2-ARE signaling pathway." (PMID 37007023, 2023). "Recently, we also demonstrate a role of SIRT1 in HIV-related kidney disease." (PMID 35795148, 2022). "In addition, some neglected areas of kidney disease deserve attention as potential emerging hotspots in the study of Sirt1, such as immune, metabolic reprogramming and fecal microbiota." (PMID 36052119, 2022). "The identification of SIRT1 modulators of natural origin, such as polyphenolic products in fruits, vegetables, and plants, demonstrated potential therapeutic effects in the prevention and treatment of kidney diseases." (PMID 35277012, 2022). "The study of mammalian sirtuins, particularly SIRT1, shows that numerous protein targets are involved in age-related pathogenesis and metabolism-related renal disorders, suggesting that the modulation of SIRT1 activity may exert strong renoprotective effects." (PMID 35277012, 2022). "We find that knockout of SIRT1 either globally or specifically in podocytes induced more albuminuria and glomerulosclerosis in Adriamycin-induced nephropathy mouse model as compared to wild-type mice with Adriamycin-induced nephropathy." (PMID 35795148, 2022). "Generally, SIRT1 exhibits a protective effect in kidney diseases." (PMID 36139886, 2022).